CD74 (CD74 molecule)
Diseases named in the same sentence as CD74 in open-access papers (continued):
Sharing a sentence is not in itself a finding about the gene and the disease.
lymphoma (continued). "Here, we investigated the ability of anti-CD20/anti-CD74 and anti-CD20/anti-IL4R bispecific antibodies to bind their designated targets on lymphoma cells and to kill their targeted cells via different mechanisms." (PMID 36353222, 2022). "Next, we determined MS4A1 (CD20), CD74 and IL4R gene expression levels in 84 lymphoma samples across different tumor stages (stage I-III/IV) and compared to expression in 12 healthy tissue controls using quantitative PCR of tissue biopsies." (PMID 36353222, 2022). "Three human genes, CD74, CXCR4, and VIM, were common to both the glioblastoma and lymphoma transplants." (PMID 25259521, 2014). "One M-GB-ADC demonstrated high specificity for CD74-expressing lymphoma cells while exhibiting minimal toxicity to non-target cells in vitro." (PMID 41677654, 2026). "Milatuzumab, a fully humanized anti-CD74 monoclonal antibody, demonstrated significant activity in preclinical lymphoma models but failed to provide meaningful benefits in clinical trials mainly due to its short half-life." (PMID 37740214, 2023). "This highlights both CD20 and CD74 as targets to facilitate direct killing of lymphoma cells without the need for effector cells." (PMID 36353222, 2022). "Taken together, these findings enabled us to demonstrate aberrant CD74-expression in ALCL cells, which might serve as tool for the development of new treatment strategies for this lymphoma entity." (PMID 34638496, 2021). "Future clinical studies should determine whether milatuzumab can indeed restore Fas-signaling and chemotherapy responses in lymphoma, CLL, and potentially other CD74-expressing malignancies." (PMID 25304249, 2014). "Thus, higher CD74 and CD44 expressions mark CD27+ memory B cells compared with CD27- naïve B cells and differ from those of malignant lymphoma B cells overexpressing CD74." (PMID 22404985, 2012). "Even more intriguing, aberrant expression or maintenance of CD74 and its fragment CLIP on solid tumor cells and lymphoma models prevents presentation of tumor antigens and favors an immune escape, which could contribute to prevention of an effective anti-lymphoma immune response in ALCL." (PMID 34638496, 2021). "This reduced tumor aggressiveness was accompanied, and possibly secondary to, a marked remodeling of the TME, which after CD74 ectopic expression was not significantly different between IRF8 WT and IRF8 mutant lymphomas." (PMID 38996030, 2024).
pancreatic cancer (18 papers, 2009 to 2025). "Although CD74 was shown to be associated to a pro-inflammatory response in several diseases, including pancreatic cancer, its role is context-dependent and depends on specific environmental cues." (PMID 39576827, 2024). "Taken together, these findings indicate CD74 as a potential diagnostic biomarker and therapeutic target for pancreatic cancer." (PMID 37629174, 2023). "Our preliminary findings indicate that CD74 is highly expressed in pancreatic cancer tissues, that increased expression is associated with a worse prognosis for patients, and that the pancreatic cancer cell line Capan-1 expresses elevated levels of CD74." (PMID 37629174, 2023). "A single-cell RNA sequencing study revealed that cancer-associated fibroblasts expressing CD74 could modulate the immune response in pancreatic tumors by activating CD4+ T cells." (PMID 37653101, 2023). "Differential analysis of the enrichment score revealed that the CD74 high expression group was significantly enriched in various cancers, such as small lung cancer, non-small cell lung cancer, pancreatic cancer, and others, within the KEGG gene set." (PMID 40470045, 2025). "The amount of apCAF (CD74+, PDGFα+) in pancreatic cancer was positively correlated with MSLN expression (P = 0.0026), but were negatively correlated with the amount of effector immune cells such as CD8+ T cells (p = 0.0165) and IFN‐γ+CD4+ T cells (p = 0.0014)." (PMID 39887656, 2025). "Overall, our study provides valuable insights into the critical role of CD74 in regulating the oncogenic properties of pancreatic cancer cells and its influence on the expression and secretion of S100A8 and S100A9." (PMID 37629174, 2023). "As both S100A8/A9 are prognostic markers for patients with pancreatic cancer, with those with a higher expression having a poorer OS, we believe that the expression levels of both CD74 and S100A8/A9 can also be crucial prognostic markers in PDAC." (PMID 37629174, 2023). "Taken together, our results indicate that CD74 plays a crucial role in regulating oncogenic cell proliferation, migration, and invasion in pancreatic cancer." (PMID 37629174, 2023). "An analysis using the gene expression profiling interactive analysis (GEPIA) database showed that the level of CD74 mRNA in 179 cases of pancreatic cancer was significantly higher than that in 171 normal tissue samples." (PMID 37629174, 2023). "The data reveal strong disparities in CD74 expression between the normal samples and tumor samples, indicating that CD74 is highly expressed in pancreatic tumor tissues." (PMID 37629174, 2023). "We investigated the role of CD74 activation in pancreatic cancer cells and its influence on oncogenic properties." (PMID 37629174, 2023). "The in vivo results thus indicate that CD74 activation in pancreatic cancer tissues promotes tumor growth and incites a pro-inflammatory TME." (PMID 37629174, 2023). "To explore the effects of CD74 suppression in pancreatic cancer cells, we performed an siRNA-mediated knockdown of CD74 in Capan-1 cells and conducted RNA sequencing (RNA-seq) on the control and CD74 knockdown cells." (PMID 37629174, 2023). "In this study, we discovered that the activation of CD74 promotes oncogenic properties in pancreatic cancer and aids in the formation of an inflammatory TME." (PMID 37629174, 2023). "Taken together, our results suggest that CD74 not only regulates the oncogenic properties in pancreatic cancer, but also has broader impacts as a TME regulator." (PMID 37629174, 2023). "We examined the molecular mechanism of CD74 action in pancreatic cancer cells and explored the broader impacts of CD74 activation on the TME." (PMID 37629174, 2023). "As reported, c8 was defined as antigen-presenting CAFs (CAFap) that overexpressed ACTA2, HLA-DRA, and CD74 55 and was enriched in pancreatic cancer." (PMID 36333338, 2022).
pancreatic cancer (continued). "In pancreatic cancer, CD74-MIF is possibly a promising target for molecular therapy, but further experimental study is needed." (PMID 35769782, 2022). "Studies have found that in pancreatic cancer, CD74 expression is related to perineural infiltration and the poor prognosis of patients after surgical resection." (PMID 36213576, 2022). "This is also accompanied by the high expression of CD74, which is a strong marker for pancreatic carcinomas with poor prognosis." (PMID 35565326, 2022). "Finally, NRG1 fusion partners were most commonly ATP1B1 (pancreatic cancer) or CD74 (NSCLC) in FDA-approved indications, with a mix of these as well as SLC3A2 and RBPMS being commonly observed partner genes in nonapproved indications." (PMID 41091579, 2025). "Furthermore, CD74 was shown to promote a pro-inflammatory tumor microenvironment in pancreatic cancer by inducing the secretion of S100A8/A9 via activation of TRAF6-NF-κB." (PMID 39425000, 2025). "First, we aimed to confirm the elevated expression of CD74 in pancreatic cancer." (PMID 37629174, 2023). "However, the precise molecular mechanisms and functional significance of CD74 in pancreatic cancer have yet to be fully understood." (PMID 37629174, 2023). "Next, we confirmed the role of CD74 in the migration and invasion of pancreatic cancer cells." (PMID 37629174, 2023). "We investigated the role of CD74 by silencing CD74 in the pancreatic cancer cell line Capan-1." (PMID 37629174, 2023). "However, the over expression of CD74 has been reported in many different malignancies, including gastric tumors, renal epithelial neoplasms, pancreatic cancers, certain types of sarcoma and skin cancer, and non-small cell lung cancers." (PMID 19602232, 2009). "The TCGA data confirm that CD74 may serve as a prognostic marker of pancreatic cancer." (PMID 37629174, 2023). "In summary, we demonstrate that CD74 regulates the expression and secretion of S100A8 and S100A9 and that these cytokines are clear prognostic markers in pancreatic cancer." (PMID 37629174, 2023). "Furthermore, CD74 immunohistochemical expression increased in higher-grade and late-stage metastatic invasive cancers compared to less aggressive and lower-grade cancers, as reported in thymic epithelial neoplasms, colorectal, gastric, and pancreatic cancers, and urothelial carcinoma of the bladder." (PMID 35208514, 2022). "In this study, CD74-MIF and BUB1 were found to be potential therapeutic targets for treating pancreatic cancer." (PMID 35769782, 2022). "CD74-COPA and CD74-APP were seldom reported, so their high enrichment also indicated the important function in tumor progression in pancreatic cancer, but this needs further verification." (PMID 35769782, 2022). "Therefore, our data indicate that both CD74 and S100A8 play crucial roles in determining the prognosis of patients with pancreatic cancer." (PMID 37629174, 2023).
Alzheimer disease (17 papers, 2008 to 2025). A progressive, neurodegenerative disease characterized by loss of function and death of nerve cells in several areas of the brain leading to loss of cognitive function such as memory and language. "CD74 has been implicated in a range of inflammatory conditions, including liver fibrosis, kidney disorders, and Alzheimer's disease." (PMID 39398062, 2024). "Previous reports suggested that the interaction between APP, COPA, and CD74 is often associated with neurodegenerative diseases, such as Alzheimer's disease." (PMID 35525962, 2022). "CD74 plays an important role in many inflammatory diseases such as skin fibrosis and Alzheimer’s disease." (PMID 39351084, 2024). "IBA1-low populations were detected in the human Alzheimer disease cortex, while simultaneously showing increased levels of—amongst others—ferritin, CD74 and CD45." (PMID 34571885, 2021). "As an example of CD74 expression in neurodegenerative disease, CD74 immunocytochemistry in Alzheimer’s disease patients showed expression within microglial processes in and around senile (neuritic and cored) plaques." (PMID 34571885, 2021). "Apart from APCs, cancer cells and podocytes, expression of CD74 is increased in smooth muscle cells undergoing inflammation and in microglia in neurodegenerative disorder such as Alzheimer disease." (PMID 21379381, 2011). "CD74 is a high affinity receptor for MIF (macrophage migration inhibitory factor) on APCs and implicated in a number of inflammatory processes in neurodegenerative affections such as Alzheimer’s disease." (PMID 33042148, 2020). "Indeed, CD74 gene transfer reduced β-amyloidosis and improved cognitive function in a mouse model of Alzheimer's disease." (PMID 29924850, 2018). "Hence, we propose DRhQ as an effective therapeutic with possible clinical applications for patients with MS as well as those with other MIF/CD74 driven CNS conditions, including ischemic injury, traumatic brain injury, methamphetamine use disorder and Alzheimer’s disease." (PMID 37933270, 2023). "CD74–APP, an intercellular interaction that is unique to Alzheimer's disease, was discovered for the first time in ACP tumor tissue." (PMID 35525962, 2022). "DRQ is thus our prime candidate for treatment of progressive MS as well other MIF/CD74-dependent inflammatory conditions, including stroke, methamphetamine abuse, traumatic brain injury, Alzheimer’s disease and GBM without the need for histocompatibility testing of DRQ recipients." (PMID 38178143, 2024).
liver fibrosis (16 papers, 2014 to 2025). "In murine models of fibrosis, MIF was anti-fibrotic; animals deficient for MIF or CD74 had higher risk for hepatic fibrosis." (PMID 24551192, 2014). "In a mouse model of chronic liver injury, CD74-deficient mice were protected from liver fibrosis." (PMID 36625344, 2023). "VA suppresses liver fibrosis by suppressing autophagy in hepatic stellate cells through inhibition of the MIF/CD74 axis." (PMID 40722864, 2025). "The downregulation of CD74 and of multiple immunostimulatory cytokines increases the rate of liver fibrosis and the proliferation of liver tumours." (PMID 39083563, 2024). "Ly6Chigh MO conversion to Ly6Clo anti-inflammatory macrophages with a restorative phenotype in murine hepatic fibrosis requires the upregulation of genes encoding molecules of the anti-inflammatory macrophage program, like CX3CR1, or with anti-fibrotic effects, like CD74." (PMID 25601191, 2015). "Furthermore, VA ameliorates liver fibrosis via the MIF/CD74 pathway stimulation." (PMID 40722864, 2025). "The progression of NAFLD to liver fibrosis can be alleviated by vanillic acid, which inhibits the autophagy of HSCs through the MIF/CD74 signaling pathway." (PMID 39175576, 2024). "While the induction of the receptors CD74 and CXCR4 is comparable between the models, there is a marked up-regulation of chemokine receptor CXCR2 in MCD-treated mice compared to the CCl4-induced liver fibrosis model." (PMID 33525493, 2021). "In a mouse model of toxic liver fibrosis, we showed that MIF exhibits hepatoprotective effects attenuating fibrogenesis by directly interfering with the activation of hepatic stellate cells via the CD74/AMPK signaling pathway." (PMID 31370326, 2019). "Circulating soluble CD74 with MIF neutralizing activity was increased in primary biliary cirrhosis and was hypothesized to contribute to liver fibrosis." (PMID 26441987, 2015).
lupus (16 papers, 2012 to 2026). "Inhibition of MIF and knockdown of CD74 protect against glomerulonephritis in lupus-susceptible mice." (PMID 36445632, 2023). "CD74 deficiency not only reduced lupus-like autoimmunity but also reduced renal pathology in chronic graft-versus-host mice." (PMID 34007409, 2021). "For instance, CD74 deficiency protects against glomerulonephritis in lupus." (PMID 37744332, 2023). "Therefore, the activation of Cd74 is associated with plentiful inflammatory diseases, such as fibrosis, T1D and systemic lupus erythematosus." (PMID 37686311, 2023). "MIF inhibition and CD74 deficiency protected against glomerulonephritis in lupus-prone mice." (PMID 32655566, 2020). "CD74 is highly expressed in multiple immune cell types, including B cells, DCs, pDCs, and macrophages —all of which mediate distinct aspects of systemic lupus erythematosus (SLE) pathogenesis." (PMID 41373904, 2025). "The role of CD74 in the activation of immune cells has been reported in systemic lupus erythematosus." (PMID 40755781, 2025). "Specifically, ligand–receptor pairs such as Thy1-(Itgam+Itgb2), Mif-(Cd74+Cxcr4), Tgfb1-(Tgfbr1+Tgfbr2), and Pecam1-Pecam1 showed higher mean expression levels in lupus mice than in DHA-treated mice." (PMID 40728997, 2025). "Specifically, two Treg subpopulations, the CCR7 and CD74 Treg subgroups, are associated with type I interferon-induced dysfunction in SLE patients, suggesting that specific pathways in lupus need to be targeted." (PMID 39294397, 2024). "Similar to our study, hCDR1 tolerance has effects on B cell activating factor (BAFF) and B-cell CD74 macrophage inhibitory factor in murine lupus." (PMID 34093553, 2021). "CD74 is also increased in human clear cell renal cell carcinoma, in B cells, and kidney of lupus mice in parallel to progression of inflammation and in the tubulointerstitium in anti-GBM nephritis, where it was expressed de novo in glomerular parietal epithelial cells and crescents." (PMID 26441987, 2015). "In parallel, NSUN4-mediated m5C modification promotes CD8+ T cell exhaustion in systemic lupus erythematosus (SLE) by elevating CD74 expression and activating CD44-mTOR-dependent mitophagy." (PMID 41424859, 2026). "B lymphocytes express elevated levels of CD74 in mouse models of SLE and lupus-prone mouse strains have elevated MIF." (PMID 32655566, 2020). "In mouse models of SLE, researchers have observed elevated levels of CD74 expression in B lymphocytes, and elevated MIF has been demonstrated in lupus-prone strains of mice." (PMID 36445632, 2023). "It was recently reported that CD74, together with CD44, is upregulated in the kidney and hippocampi of diseased lupus-prone mice and was reduced by treatment with the tolerogenic peptide hCDR1." (PMID 22404985, 2012). "In lupus-prone mouse strains, the upregulation of MIF and CD74 was also positively correlated with worsening renal inflammation, whereas lupus mice lacking the MIF or CD74 receptor are protected from LN, demonstrating the role of the MIF-CD74 axis in the pathogenesis of LN." (PMID 35563296, 2022).